INS (insulin)
Diseases named in the same sentence as INS in open-access papers (continued):
Sharing a sentence is not in itself a finding about the gene and the disease.
diabetes (continued). "Metabolic illnesses mostly resulting from dysregulated energy balance, insulin resistance, and abnormalities in lipid metabolism include diabetes, obesity, and dyslipidemia globally." (PMID 40430848, 2025). "Maturity-Onset Diabetes of the Young (MODY) encompasses genetically heterogeneous, autosomal dominant forms of diabetes characterized by impaired insulin secretion due to pancreatic beta-cell dysfunction." (PMID 41020216, 2025). "Type 1 diabetes mellitus (T1DM) is an autoimmune disease leading to destruction of pancreatic β-cells and loss of insulin production ability." (PMID 40979707, 2025). "Modern medicine mainly controls the course of diabetes by oral hypoglycemic drugs or subcutaneous insulin injection, but some patients’ blood glucose levels are difficult to control in an ideal manner, resulting in frequent complications." (PMID 40650120, 2025). "With diabetes becoming more prevalent, the number of people flying with insulin-treated diabetes is increasing and consequently the number of both pilots and air passengers treated with CSII is also rising." (PMID 39496965, 2025). "We found that the factors with the greatest impact on the prevalence of diabetes were glycohemoglobin, glucose, fasting blood glucose, age, cholesterol, osmotic pressure, BMI, blood urea nitrogen, and insulin." (PMID 40313792, 2025). "Studies suggest that PCs can lower blood glucose, improve insulin resistance, regulate insulin secretion, protect pancreatic β-cells in diabetic patients, and effectively alleviate diabetes complications." (PMID 39995417, 2025). "The most frequent diabetes treatment was oral hypoglycemic medication (58.2%), followed by insulin (35.5%) and a diabetic diet only (18.7%)." (PMID 41517299, 2025). "The increasing prevalence of Type 1 Diabetes Mellitus (T1D) has led to the development of advanced technologies such as Continuous Glucose Monitors (CGMs) and insulin infusion pumps." (PMID 41200730, 2025). "Since its discovery in 1921, insulin has played a major role in diabetes treatment, especially in insulin analogs." (PMID 40070573, 2025). "In Brazil, most individuals with diabetes receive human insulin and treatment supplies from the government." (PMID 40008736, 2025). "Moderate exercise lowers fasting glucose and HbA1c, up-regulates BDNF, improves insulin sensitivity and restores brain insulin signalling, directly counteracting these diabetes-specific insults." (PMID 41460428, 2025). "Although there are minimal international data that can confirm error occurrence by age range, the National Diabetes Inpatient Audit (NADIA) confirmed that 65% of insulin errors in English hospitals occurred while treating people aged over 65 years." (PMID 41358572, 2025). "Diabetes Mellitus (DM), a complex metabolic condition arising from the interplay between hereditary predisposition and environmental influences, manifests through compromised insulin action, inadequate hormone production, and disrupted glucose regulation." (PMID 40692596, 2025). "While T1D is an autoimmune disease characterized by the destruction of insulin-producing beta cells, MODY is a monogenic form of diabetes caused by mutations in a single gene affecting beta-cell function." (PMID 39860389, 2025). "History of hypertension, diabetes, stroke, cardiovascular disease (CVD), and chronic kidney disease, insulin use, and medication for hypertension and diabetes were assessed as core, whereas foot ulcer in the past year was assessed as optional." (PMID 40791630, 2025). "Poor glycemic control in diabetic patients exacerbates periodontal inflammation, while periodontitis can impair insulin sensitivity and glycemic control, complicating diabetes management." (PMID 40283848, 2025). "Elevated adipose-derived MIF in obesity and diabetes further impairs insulin signalling and amplifies pro-inflammatory cascades, thereby reinforcing insulin resistance." (PMID 41036138, 2025).
diabetes (continued). "Rats with alloxan-induced diabetes who were given syringic acid (50 mg/kg for 30 days) showed an increase in insulin and C-peptide levels and a decrease in plasma glucose levels." (PMID 39861406, 2025). "These technologies facilitate more accurate insulin dosing and frequent glucose monitoring, potentially easing life with diabetes and improving glycemic outcomes." (PMID 39172172, 2025). "For advanced diabetes technologies like continuous glucose monitoring and insulin pumps, the situation is even more challenging." (PMID 40358737, 2025). "describe the chrononutrition factors (meal regularity, meal timing and meal frequency) applied in various populations and their effect on glycemic outcomes (glucose indices, insulin indices and incidence of diabetes) of the populations." (PMID 39951411, 2025). "Diabetes is a serious, chronic condition that occurs when the body cannot produce enough insulin or cannot use the insulin that it does produce, leading to high levels of glucose." (PMID 40573277, 2025). "Obesity and diabetes are often accompanied by insulin resistance, manifested as increased levels of serum insulin and decreased sensitivity of tissues to insulin." (PMID 39948335, 2025). "For instance, diabetes often leads to increased insulin resistance, which impairs glucose uptake in muscle cells and reduces the efficiency of muscle protein synthesis." (PMID 40075050, 2025). "Adipose-specific overexpression of Mig-6 improves systemic glucose tolerance and insulin sensitivity, suggesting its potential as a target for both the treatment and prevention of diabetes." (PMID 39937764, 2025). "Recombinant human insulin, developed from genetically modified E. coli or yeast, is a cornerstone treatment for diabetes, offering a reliable and safe alternative to animal-derived insulin." (PMID 41012519, 2025). "The discovery of insulin 327 and its hepato-preferential effect is a testament to innovative strategies which aim to prioritise the management of diabetes within physiological limits." (PMID 41155876, 2025). "Diabetes mellitus is a chronic metabolic disorder marked by persistent high blood sugar levels due to impaired insulin secretion, insulin action, or both." (PMID 41464450, 2025). "Diabetes mellitus is a multifaceted chronic disorder characterized by insulin resistance or inadequate insulin secretion from pancreatic β-cells, leading to elevated blood glucose levels." (PMID 40299682, 2025). "Islet cell autoantibodies, glutamate-decarboxylase (GAD) autoantibodies, and thyroid peroxidase antibodies were positive; stimulated c-peptide and insulin levels were low, indicating type 1 diabetes mellitus (T1D)." (PMID 40612706, 2025). "Zudem unterstützen KI-basierte Systeme die Therapie von Kindern mit Diabetes mellitus Typ 1 durch automatisierte Insulin-Dosierungssysteme (AID)." (PMID 40586805, 2025). "Differential diagnoses initially included type 1 diabetes mellitus, due to early-onset insulin-requiring hyperglycemia, and acquired generalized lipodystrophy (AGL), given the absence of prior genetic testing." (PMID 41341138, 2025). "Intensive analysis of perturbed pathways is highly important, especially in diabetes where genes and proteins with high correlations were found to be involved in pathways related to insulin signaling, e.g., fatty acid metabolism and mTOR signaling." (PMID 41007744, 2025). "Despite advancements in diabetes technology and insulin formulations, maintaining optimal glycemic outcomes remains challenging in these individuals." (PMID 40022528, 2025). "In diabetes with insulin dysfunction, the proinflammatory lipid mediators are upregulated and the intensity of the switch was decreased, contributing to chronic inflammation and also the insulin resistance." (PMID 41030912, 2025).
diabetes (continued). "The DIGAMI (Diabetes Mellitus, Insulin–Glucose Infusion in Acute Myocardial Infarction) study provided evidence that intensive insulin treatment does not result in better cardiovascular outcomes compared with sulfonylurea therapy." (PMID 41302503, 2025). "The abilities of ondansetron to reduce glucose levels and enhance the sensitivity of insulin are the main factors that contribute to diabetes treatment." (PMID 40356976, 2025). "Diabetes mellitus (DM) type 1 and 2 is a chronic metabolic disease characterized by impaired regulation of blood glucose levels due to either insulin deficiency or reduced insulin sensitivity." (PMID 40647303, 2025). "Insulin treatment is common for type 1 diabetes mellitus (T1DM) patients and also common for T2DM patients when diet, exercise, weight loss, and oral hypoglycemic agents have not improved glycemic control." (PMID 40734861, 2025). "Insulin lispro is commercially available at a concentration of 100 units/mL, and daily insulin requirements vary widely among diabetic patients depending on individual factors such as diabetes type, body weight, diet, and physical activity." (PMID 40733109, 2025). "Activated AMPK stimulates glucose uptake in various tissues, increasing insulin-mediated skeletal muscle glucose uptake in rodent diabetes models." (PMID 40136665, 2025). "β-blocker carvedilol attenuated insulin-induced PDE4D induction and restored cAMP level to prevent diabetes-associated cardiac dysfunction." (PMID 40015131, 2025). "We present the case of a 53-year-old female with type 2 diabetes mellitus who developed EuDKA following the abrupt discontinuation of long-term insulin therapy and transition to an SGLT2 inhibitor." (PMID 40376133, 2025). "Approximately 20% of cardiac surgery patients have pre-existing diabetes mellitus, many of which require insulin therapy." (PMID 40141772, 2025). "The enhanced antioxidant activity observed in the optimized extract is particularly relevant for diabetes management, as strong antioxidants can help restore redox balance, protect pancreatic β-cells, and improve insulin sensitivity." (PMID 40807540, 2025). "In rodent models, treatment with HN or its analogs enhances insulin action, decreases blood glucose levels, and prevents early diabetes progression, suggesting its utility as a therapeutic candidate." (PMID 41465308, 2025). "This approach is particularly valuable in managing chronic conditions such as diabetes, where smart drug delivery systems provide real-time glucose monitoring and insulin release." (PMID 40283294, 2025). "Previous research demonstrated that high-glucose exposure modulates genes involved in insulin secretion and diabetes prevention in MSCs derived from the decidua basalis of the human placenta." (PMID 39954213, 2025). "It regulates glucose and lipid metabolism, improves insulin sensitivity, and helps control blood glucose levels, making it a promising candidate for managing diabetes and metabolic syndrome." (PMID 41254699, 2025). "Glycohemoglobin, glucose, fasting glucose, age, cholesterol, osmolality, BMI, blood urea nitrogen, and insulin were found to exert the greatest influence on the prevalence of diabetes." (PMID 40313792, 2025). "For enhanced insulin absorption and efficiency in diabetes control, these systems generally rely on two types of polymers: natural and synthetic." (PMID 40574088, 2025). "Administration of S. maxima and S. platensis in capsule form can reduce fasting blood glucose levels and improve insulin sensitivity in people with obesity, overweight, diabetes mellitus, and hypertension." (PMID 40182955, 2025). "For people with diabetes on insulin, optimal glycaemic management can be hindered by missed or mistimed insulin doses." (PMID 41039947, 2025). "We present a case of a patient with a history of partial pancreatectomy and insulin-dependent T2DM, who demonstrated brittle diabetes with marked sensitivity to insulin, and was ultimately diagnosed with T3cDM." (PMID 41146800, 2025).
diabetes (continued). "Diabetes Mellitus (DM) is a chronic condition that occurs when the body cannot produce enough insulin or cannot use insulin efficiently." (PMID 40334207, 2025). "Diabetes-induced hyperglycemia impairs hippocampal function by disrupting insulin signaling pathways, leading to synaptic dysfunction and memory deficits." (PMID 41268302, 2025). "Higher dose dexamethasone was associated with a greater hazard of a severe hyperglycemic event, particularly in patients with diabetes, but with an average increase in PG like that of the standard dose group and similar needs of insulin." (PMID 40665171, 2025). "As the oral DI accurately represents β‐cell insulin secretory rates in the context of insulin resistance, it has been established as a metabolic predictor of progression to diabetes." (PMID 40270326, 2025). "Recent research has identified specific determinants of HbA1c variability, including ethnicity, insulin use, and triglyceride levels, with variability independently predicting mortality across different types of diabetes." (PMID 41301738, 2025). "For instance, medication reminder apps have been shown to enhance adherence in diabetes management by ensuring timely insulin administration." (PMID 40239197, 2025). "Insulin dysregulation in both type 1 and 2 diabetes affects neurotransmitter systems, neuronal energy metabolism, and neurogenesis." (PMID 39822993, 2025). "Studies have demonstrated improvements in glycaemic control in cases of obesity and diabetes mellitus, reduced insulin requirements, and halted disease progression in recently diagnosed type-1 diabetics by preserving endogenous insulin production." (PMID 40559778, 2025). "While insulin is commonly prescribed due to physician familiarity and the growing complexities of diabetes medications, it is essential to recognise it is one of many treatment options for managing type 2 diabetes, unlike type 1 diabetes." (PMID 39511718, 2025). "Initiation of insulin for a short term early after diagnosis in such situations improves glycaemic control and improves insulin secretion with long‐lasting effects on diabetes control." (PMID 40482054, 2025). "Type 2 diabetes mellitus (T2DM) is a condition characterized by hyperglycemia due to inadequate insulin secretion and insulin resistance." (PMID 39949546, 2025). "This suppression can affect insulin production and release, which can contribute to diabetes and kidney disease, potentially leading to severe complications." (PMID 40137174, 2025). "Five distinct clusters of diabetes have been proposed, of which mild age-related diabetes is the most common, making up 40% of diabetes diagnoses, and is directly attributable to ageing-related ectopic fat deposition and insulin resistance." (PMID 38710803, 2025). "Diabetes Mellitus (DM) is a complex metabolic disorder characterized by hyperglycemia, primarily arising from insufficient insulin secretion or the development of insulin resistance." (PMID 40964162, 2025). "These advances hold the promise of revolutionizing the way insulin is delivered, reducing the burden of disease management and enhancing the overall quality of life for millions of individuals living with diabetes." (PMID 40352348, 2025). "For instance, in models of obesity and diabetes, flies can be treated with various compounds to assess their effects on lipid metabolism, insulin sensitivity and glucose homoeostasis." (PMID 39722550, 2025). "M. charantia has demonstrated promising effects in avoiding diabetes mellitus and delaying the progression of diabetic sequelae, such as neuropathy, gastroparesis, nephropathy, waterfall, and insulin blockage, in experimental animal models." (PMID 40184394, 2025). "The case series analysis highlighted the critical role of uninterrupted access to insulin and other diabetes medications in maintaining or improving glycemic control." (PMID 41008502, 2025).
diabetes (continued). "Non-insulin-treated diabetes (OR: 6.93; 95% CI: 3.78–12.73), hypothyroidism (OR: 1.78; 95% CI: 1.02–3.11), and male sex (OR: 2.33; 95% CI: 1.36–4.00) were independently associated with increased DCM risk." (PMID 41153651, 2025). "Each of these molecular targets plays a role in managing different aspects of insulin sensitivity and glucose metabolism, contributing to the overall control of diabetes." (PMID 40771585, 2025). "A systematic review and meta-analysis showed that diets with a low GL decrease insulin levels and can be used in the management of diabetes." (PMID 40566351, 2025). "The risk of developing active tuberculosis is three times higher among those with a hemoglobin A1c (HbA1c) level ≥7.0% than those with an HbA1c level <7.0%, and twice as high among patients with Diabetes Mellitus (DM) using ≥40 daily units of insulin." (PMID 40910054, 2025). "Based on these advantages, needle‐free injection has been recommended as one of the insulin delivery methods in the Chinese Diabetes Injection Guidelines." (PMID 41180388, 2025). "Chronic low-grade inflammation, or “meta-inflammation,” is a hallmark of type 2 diabetes mellitus (T2DM), that disrupts glucose metabolism and insulin signaling in adipocytes, hepatocytes, and muscle cells." (PMID 41480362, 2025). "The molecular links between dysregulated insulin signaling in AD and diabetes raise the prospect of novel therapeutic strategies for AD, based on antidiabetic agents." (PMID 40943177, 2025). "Diabetes mellitus is a chronic metabolic disease characterized by dysregulated blood glucose levels resulting from inadequate insulin production or reduced insulin sensitivity." (PMID 41372351, 2025). "This difference remained when adjusting for age, sex, diabetes duration, and previous treatment with multiple daily insulin injections or insulin pump (P = .008)." (PMID 38629871, 2025). "Thirdly, in addition to high glucose, elevated fatty acids and insulin are also prevalent in the context of diabetes." (PMID 39950114, 2025). "Diabetes mellitus is impaired insulin secretion and variable degrees of peripheral insulin resistance leading to hyperglycemia." (PMID 40238299, 2025). "In total, 37 patients (35.7% of the population) had diabetes, 25 (67.56%) of whom received oral hypoglycemic medications, and 12 (32.43%) patients received insulin alone or in combination with oral hypoglycemic medications." (PMID 41007750, 2025). "In one study, Moringa leaf extract was initiated to meaningfully lessen blood glucose levels and improve insulin sensitivity in rats that had been induced to diabetes by alloxan." (PMID 40248126, 2025). "The replacement of exogenous insulin is a commonly used clinical treatment modality for Type 1 diabetes mellitus, which is characterized by the degeneration of beta cells." (PMID 41438817, 2025). "Elderly diabetes patients with hip fractures, those using insulin, or those newly diagnosed with T2DM had lower VD levels." (PMID 40313432, 2025). "The phytoconstituents are believed to act synergistically in regulating blood glucose, improving insulin dynamics, and combating oxidative stress, suggesting their potential use in managing diabetes mellitus." (PMID 41155632, 2025). "Increased frequency of larger islets is usually seen in conditions with increased insulin demand like insulin resistance, obesity, pregnancy, and diabetes." (PMID 40809458, 2025). "Type 2 Diabetes Mellitus (T2DM) is increasingly affecting individuals across various age groups due to inadequate insulin action and secretion." (PMID 41007838, 2025). "Diabetes mellitus (DM) is a chronic metabolic disease characterized by persistent hyperglycemia and impaired protein, carbohydrate and fat metabolism, due to insulin dysregulation." (PMID 40922493, 2025). "The IMS score components involve diabetes duration, number of diabetes medications, insulin use, and HbA1c." (PMID 40005466, 2025).